AFP (alpha fetoprotein)
Diseases named in the same sentence as AFP in open-access papers (continued):
Sharing a sentence is not in itself a finding about the gene and the disease.
hepatocellular carcinoma (continued). "A model to estimate survival for hepatocellular carcinoma MESH, introduced in 2016, is a score based on the Milan criteria, the presence and type of vascular invasion, C-P score, performance status, and laboratory parameters (AFP and alkaline phosphatase)." (PMID 36624801, 2022). "The presence of hepatocellular carcinoma was documented either using computed tomography (CT), magnetic resonance imaging (MRI), or contrast-enhanced ultrasonography (CEUS), in correlation with serum levels of alpha-fetoprotein." (PMID 35800821, 2022). "AFP can activate the PI3K/AKT signalling, stimulates the transcription cofactor mTOR, STAT3, HIF‐1α and Bcl‐2, which regulates the expression of oncogenes, as well as promotes angiogenesis and the growth of the hepatoma cells." (PMID 36181321, 2022). "Hepatoid adenocarcinoma of the stomach (HAS) is a subset of gastric cancer (GC) histologically characterized by hepatocellular carcinoma-like foci with or without alpha-fetoprotein secretion, which is easily misdiagnosed." (PMID 36010842, 2022). "Investigations like alpha-fetoprotein and carcinoembryonic antigen levels may help differentiate PHL from hepatocellular carcinoma but these tests lack sensitivity and specificity." (PMID 35800829, 2022). "Through a multicenter cross-sectional study, a biomarker combination consisting of Phe-Trp and GCA was identified and used as a test for hepatocellular carcinoma (HCC), and they were further developed as an effective tool to verify AFP false-negative HCC patients and high-risk S-HCC patients." (PMID 36139459, 2022). "Alpha-fetoprotein levels along with abdomen ultrasound can be used to screen for hepatocellular carcinoma, even though there are no validated surveillance protocols to date." (PMID 35725468, 2022). "In addition, local alignment analysis revealed high similarity between this AFP C-terminal SLiM and AXIN 2, a protein involved in the WNT pathway, which is deregulated in CRC and hepatocellular carcinoma." (PMID 36496998, 2022). "Therefore, DEN (200 mg/kg) was used for the induction the hepatocellular carcinoma (HCC) and the level of serum alpha fetoprotein was used for the estimation and confirmation of HCC." (PMID 35889371, 2022). "Hepatoid adenocarcinoma of the stomach (HAS) is a subset of gastric cancer (GC) histologically characterized by hepatocellular carcinoma-like foci with or without alpha-fetoprotein (AFP) secretion." (PMID 36010842, 2022). "Therefore it is recommended to use a combination of AFP testing with other factors, such as platelets and age, CEA and CA-19-9, and microRNAs, for hepatocellular carcinoma screening." (PMID 36293285, 2022). "While few of them have good clinical application value, most of them have not been studied specifically for the diagnosis of AFP-negative hepatocellular carcinoma." (PMID 33889548, 2021). "During hepatoma progression, this biological process could be reversed by aberrantly low HBP1 expression, which promotes AFP effect on PTEN, MMP9 and caspase-3, thus induces proliferation and migration, and inhibits apoptosis in hepatoma cells." (PMID 33794968, 2021). "The level of AFP-L3 in serum will increase linearly with the growth of hepatocellular carcinoma, which has a relatively high specificity for the diagnosis of liver cancer, and it will not be restricted by the rule of AFP ≥ 400 μg/L." (PMID 33971914, 2021). "The repression of AFP by HBP1 attenuates AFP effect on PTEN, MMP9 and caspase-3, thus inhibits proliferation and migration, and induces apoptosis response to oxidative stress in hepatoma cells." (PMID 33794968, 2021). "Prior evidence has indicated that miR-338-5p was proposed to be a biomarker for the diagnosis of hepatocellular carcinoma owing to its negative correlation with the level of AFP." (PMID 33882457, 2021).
hepatocellular carcinoma (continued). "AFP co-localized and interacted with PTEN inducing, thereby, CXCR4 chemokine receptor expression by activating Akt/mTOR signaling pathway and stimulating migration of hepatoma cells." (PMID 33562077, 2021). "Alpha-fetoprotein-negative hepatocellular carcinoma (AFP-NHCC) (< 8.78 ng/mL) have special clinicopathologic characteristics and prognosis." (PMID 33685417, 2021). "Thus, it is obvious that STK1p is more useful than AFP and CEA to distinguish pre-liver carcinoma groups." (PMID 34258026, 2021). "When they are used, integral AUC values are above the average, the level of these tumor markers in the blood of patients with hepatocellular cancer does not correlate with alpha-fetoprotein." (PMID 34513063, 2021). "For example, a single 30-year-old white female with a 20 mm tumor on her liver with no metastasis detected, no elevated AFP, and a well-differentiated hepatocellular carcinoma on biopsy, treated with radiofrequency ablation." (PMID 34187430, 2021). "Even in AFP‐negative hepatoma cells, exogenous AFP administration can significantly increase the proliferation of cancer cells." (PMID 33090723, 2020). "The same group has successfully used transcriptional targeting by AAV vector-mediated HSV/TK gene transfer under the control of an alpha-fetoprotein enhancer and albumin promoter to specifically target AFP-positive human hepatocellular carcinoma cells in a nude mouse model." (PMID 32674264, 2020). "Our data indicated that AFP could significantly promote the proliferation and weaken ATRA‐induced apoptosis of hepatoma cells." (PMID 33090723, 2020). "We hypothesized that AFP could interfere with the RA‐RAR signalling pathway by binding with RAR, and thereby inhibiting the transcriptional regulation of RAR in hepatoma cells." (PMID 33090723, 2020). "For example, alpha-fetoprotein has various glycoforms that are used in the detection of hepatocellular carcinoma and non-seminomatous germ cell tumours." (PMID 31936170, 2020). "We generated human hepatoma SMMC-7721 cell lines with or without recombinant AFP transfection (AFPup and control groups)." (PMID 32774373, 2020). "AFP has 3 isoforms: L1 is produced in non-neoplastic liver disease, L2 is produced in yolk sac tumours, and L3 is produced in hepatocellular carcinoma and hepatoblastoma." (PMID 31652641, 2019). "The biomarkers alpha-fetoprotein (AFP) and protein induced by vitamin K absence/antagonist-II (PIVKA-II) may be useful for detecting early-stage hepatocellular carcinoma (HCC)." (PMID 30675135, 2019). "The combined detection of serum AFP and secreted protein DKK1 could be used as an important way to improve the sensitivity and accuracy of clinical diagnosis of primary hepatic carcinoma." (PMID 31428352, 2019). "We found that AFP, CA724, CA153, CEA, CA125, CA199 and PSA were expressed in both unfractionated plasma and exosomes of patients with hepatocellular carcinoma, gastric carcinoma, breast cancer, colon cancer, ovarian cancer, pancreatic carcinoma and prostate cancers, respectively." (PMID 33833900, 2019). "Hepatoma arterial-embolization prognostic (HAP) score, which consists of four tumor-related variables (alpha-fetoprotein [AFP] level and tumor size) and liver function-related variables (serum albumin and total bilirubin levels), has been proposed for predicting outcomes after TACE." (PMID 30991968, 2019). "Second, the specificity and sensitivity of CEA for CRC prognosis were not as high as the AFP for hepatocellular carcinoma, and some CRC cases didn’t accompany with high CEA or just accompanied with other tumor marker increasing, for example CA19-9." (PMID 30513126, 2018).
hepatocellular carcinoma (continued). "AFP-L3, a well-known serum biomarker of hepatocellular carcinoma determined by the ratio between fucosylated (L3) and nonfucosylated (L1 and L2) AFP, has several advantages." (PMID 29265394, 2018). "At present, the traditional tumor biomarker alpha-fetoprotein (AFP) is used to predict the prognosis of patients with hepatocellular carcinoma, but its sensitivity and specificity are not satisfactory." (PMID 30687735, 2018). "Although serum AFP is primarily used as a marker for hepatocellular carcinoma, it can be also regularly elevated in a range of nonneoplastic liver diseases such as acute liver injury with extensive necrosis." (PMID 30245889, 2018). "High post-operative serum alpha-fetoprotein level and multiple tumors, but not inflammatory factors, were risk factors for poor prognosis in HBV-related hepatocellular carcinoma patients after resection." (PMID 29930697, 2018). "The situation of positive TgAb invalidating Tg is somewhat like alpha-fetoprotein negative scenario in hepatocellular carcinoma." (PMID 30200153, 2018). "Although there are no reports of AFP-producing rectal cancer treated with radiation therapy, several reports in hepatocellular carcinoma and a few reports in yolk sac tumor have shown its effectiveness." (PMID 30191347, 2018). "For example, Yang yuewu found that the expression of c-jun in hepatocellular carcinoma (HCC) correlates with HBsAg, AFP, tumor diameter, tumor capsule, tumor vascular invasion and so on, suggesting the c-jun may play an important role in the occurrence and development of liver cancer." (PMID 30671125, 2018). "Therefore, we speculated that the concentration of AFP may be positively related to the capacity for liver regeneration in the condition of acute liver injury on the basis of chronic liver diseases, apart from malignancies such as hepatocellular carcinoma and gastric cancer." (PMID 29854714, 2018). "The results were inconclusive since there was not enough evidence to evaluate the value of alpha-fetoprotein or ultrasound screening, or both, for patients with hepatocellular carcinoma who were positive for hepatitis B surface antigen (HBsAg)." (PMID 28813112, 2017). "The European Association for the Study of Liver (EASL) and American Association for the Study of Liver Diseases (AASLD) guidelines do not even recommend AFP as a diadynamic criteria of hepatocellular carcinoma." (PMID 28060739, 2017). "However, only alpha-fetoprotein (AFP) and CA15-3 are clinically monitored for their glycan changes in the therapy for hepatocellular carcinoma and breast cancer, respectively." (PMID 28894650, 2017). "The proof of this concept was demonstrated in a 1999 study in which an adenovirus was placed under the control of the α-fetoprotein (AFP) gene promoter and shown to replicate in a hepatocellular carcinoma cell line expressing AFP but not in normal human cells." (PMID 28712033, 2017). "Alpha-fetoprotein (AFP) is a well-known embryonal serum protein that is mainly produced by fetal liver cells and yolk sac cells and commonly serves as an important tumor marker for hepatocellular carcinoma or yolk sac tumors." (PMID 28423604, 2017). "The diagnosis of early, small and alpha-fetoprotein (AFP)-negative primary hepatic carcinomas (PHCs) remains a significant challenge." (PMID 27590520, 2016). "High expression of hepatic vascular endothelial growth factor and hepatic platelet-derived endothelial cell growth factor was found to relate to poor prognosis in AFP-negative hepatocellular carcinoma patients after curative resection." (PMID 27689999, 2016). "This is unlike certain other cancers, such as hepatocellular carcinoma that has alpha-fetoprotein (AFP) and prostate cancer that has the tumor-specific prostate marker (PSA), to name a couple." (PMID 26797527, 2016).
hepatocellular carcinoma (continued). "Similarly, in patients with underlying liver cirrhosis, an elevated AFP level, together with characteristic findings on multiphase imaging, is sufficient to establish a diagnosis of hepatocellular carcinoma (HCC) and a biopsy is not recommended." (PMID 28042579, 2016). "As a type of specific tumor antigen in the membrane and cytoplasm of cells, α-fetoprotein (AFP) is positive in over 70% of primary hepatic carcinomas, but negative in normal liver or other normal tissues." (PMID 26981334, 2016). "AFP has long been considered a marker for monitoring hepatocellular carcinoma treatment but is not reliable in some cases." (PMID 25822740, 2015). "For instance, alpha-fetoprotein (AFP), a widely accepted biomarker of hepatocellular carcinomas (HCC), in some patients with advanced HCC may still be negative." (PMID 26561538, 2015). "We found that the levels of miR145, miR146a and miR146b were lower in 5 cases of AFP negative hepatoma patients sera compared with those in 4 cases of normal sera, showing a negative correlation with the expression level of VASN." (PMID 25826090, 2015). "Fifteen out of 40 HCC patients (37%) had low AFP (<20 ng); from those 15 patients, only 1 patient had MDK <0.387 ng/mL; this shows that MDK had an outstanding performance for distinguishing hepatocellular carcinomas from liver cirrhosis even in patients with AFP <20 with sensitivity reaching 93.3%." (PMID 25737783, 2015). "HBx priors to drive the expression of AFP and AFPR to promote expression of Src in normal liver cells and hepatoma cells; AFP and AFPR maybe play pivotal role in HBV-related hepatocarcinogenesis; Targeting AFPR is an available therapeutic strategy of HCC." (PMID 25943101, 2015). "The lesion was unlikely a hepatocellular carcinoma or hepatoblastoma, since both AFP and HepPar-1 were negative." (PMID 26187280, 2015). "Other markers such as CA125 (MUC126) and AFP (alpha fetoprotein) are not cancer specific; nevertheless, their high levels in serum are used for early diagnosis of ovarian cancer and hepatocellular carcinoma, respectively." (PMID 26325576, 2015). "About 30% to 40% of patients with hepatocellular carcinoma (HCC) are serum AFP negative clinically, a growing trend in recent years." (PMID 25826090, 2015). "A study published in 1988 using 139 patients over a 4 year period noted that the frequency of AFP negative or low-level AFP hepatocellular carcinoma patients has been increasing gradually." (PMID 26341083, 2015). "We report a case of a young professional bodybuilder with self-administration of high-doses of anabolic androgenic steroids (AAS) for at least 6 years who developed a hepatocellular carcinoma (HCC) without metastasis or alpha-fetoprotein elevation." (PMID 25986067, 2015). "Serum alpha-fetoprotein (AFP) concentration, serum alanine transaminase (ALT), aspartate transaminase (AST), and alkaline phosphatase (ALP) activities were also determined for confirmation of hepatocellular carcinoma induction." (PMID 25136637, 2014). "As demonstrated by Dual Luciferase Assay, various AFP promoter based enhancer sytems specifically and optimally expressed luciferase in hepatoma models HepG2 and Huh7 but not in untransformed Chang Liver and non liver CHO cells." (PMID 25108398, 2014). "In fact it was considered as alpha-fetoprotein-negative hepatocellular carcinoma, possibly of the fibrolamellar pattern." (PMID 25165610, 2014). "In 2 of 13 cells, the PTP4A3/PRL-3 mRNA levels were lower than in the known cell lines such as HLE and HLF derived from epithelial and fibroblastic colonies in cultures of the same undifferentiated hepatomas and did not produce AFP and albumin." (PMID 23064776, 2013). "In hepatocellular cancer, AFP becomes active again, a mechanism which is not yet fully clarified yet." (PMID 23734827, 2013).
hepatocellular carcinoma (continued). "The transcriptional activity of the AFpg promoter was tested in various cell types, including an AFP-positive human hepatoma cell lines (HepG2 and Hep3B), an AFP-negative human hepatoma cell line (SK-Hep-1), and a normal human liver cell line (L-02)." (PMID 23173703, 2012). "Cases with subcutaneous metastasis of differentiated hepatocellular carcinoma to the abdominal wall without prior seeding as a consequence of local interventions with a negative or normal alpha-fetoprotein level in the serum are extremely rare." (PMID 22647077, 2012). "Cases with subcutaneous differentiated metastasis of hepatocellular carcinoma with a negative or normal alpha-fetoprotein (AFP) level in the serum are extremely rare." (PMID 22647077, 2012). "We present a case of a 75-year-old man with singular abdominal wall metastasis of differentiated, AFP-negative hepatocellular carcinoma without a history of prior seeding and without prior surgery to the abdominal wall." (PMID 22647077, 2012). "The second component was a moderately differentiated hepatocellular carcinoma that was positive for hepatocellular antigen and AFP and negative for neuroendocrine markers." (PMID 29147223, 2011). "In the early days of HAC definition, it was suggested that HAC developed from AFP-producing gastric cancer in which extensive hepatoid differentiation rarely occurred because not all AFP-producing gastric cancers resemble hepatocellular carcinoma." (PMID 21592404, 2011). "In adults, serum AFP is elevated in patients with hepatocellular carcinoma, yolk sac tumors, and noncancerous liver disease." (PMID 21592404, 2011). "As many patients with liver carcinoma have liver cirrhosis, but not normal liver, and some liver cirrhosis are AFP positive." (PMID 22040050, 2011). "Alphafaetoprotein [(AFP), AFLP (Lens culinaris –a derivative for AFLP)] and DCP (des- carboxy prothrombin) are the most utilized popular cancer biomarkers for liver cancer or hepatocellular carcinoma (HCC) known so far." (PMID 24281040, 2010). "This case reminds clinicians that in looking for likely hepatocellular carcinoma recurrence, when no detectable hepatic lesion can account for an elevated alpha-fetoprotein level, the gall bladder should be included in the search for the site of metastasis." (PMID 19830175, 2009). "Serum protein induced by vitamin K absence or antagonist II (PIVKAII), hepatoma-specific band of serum gamma-glutamyl transferase (GGTII), and α-fetoprotein (AFP) levels were determined in 120 patients with hepatocellular carcinoma (HCC) and 90 patients with cirrhosis." (PMID 12799630, 2003). "It was found that there was a high correlation between hepatoma cell number and AFP secretion after treatment and that the amount of AFP secreted per cell per 72 h was not affected with therapeutically achievable concentrations." (PMID 2469455, 1989). "Similarly, in alpha-fetoprotein-negative hepatocellular carcinoma (AFP-negative HCC), both SPP1+ TAMs and CD44 expression on T cells and tumor cells are highly enriched." (PMID 41425545, 2025). "This is mainly due to the fact that certain hepatocellular carcinomas are AFP-negative and that AFP might be released in liver diseases, such as cirrhosis." (PMID 38671768, 2024). "Hepatoid adenocarcinoma (HAC) is a rare type of extrahepatic adenocarcinoma with production of alpha-fetoprotein (AFP), which has a morphological phenotype of hepatocellular carcinoma (HCC)." (PMID 38167074, 2024). "These days, AFP testing is not useful for screening HCC in patients with AFP-negative hepatocellular carcinoma (AFP-NHCC), which has been detected in a large number of HCC patients." (PMID 39859975, 2024). "After years of research on AFP, we know that an elevated level in maternal serum may result not only from fetal disorders but also from a neoplastic process in the pregnant woman, such as hepatocellular carcinoma (HCC), germ cell tumors, or hereditary persistence of AFP (HPAFP)." (PMID 38256600, 2024).